CXCL10 (C-X-C motif chemokine ligand 10)
Diseases named in the same sentence as CXCL10 in open-access papers (continued):
Sharing a sentence is not in itself a finding about the gene and the disease.
stomach adenocarcinoma (1 paper, 2020). "Expression of CXCL9 and CXCL10 was positively correlated with infiltrating levels of CD8+ T cells in stomach adenocarcinoma." (PMID 33323542, 2020). "High expression of CXCL9 and CXCL10 correlated positively with infiltrating levels of CD4+ T and CD8+ T cells in stomach adenocarcinoma." (PMID 33323542, 2020).
tendinopathies (1 paper, 2024). "However, the production of TNFα and CXCL10 chemokine and transient PMN cell infiltration in tendinopathies is independent of ASC inflammasomes." (PMID 39468985, 2024).
Thrombocytosis (1 paper, 2021). Increased numbers of platelets in the peripheral blood. "In PMF patients, the elevation of CXCL10 was associated with thrombocytosis and decreased levels of CXCL10 and IL-17 with erythropenia, while in ET patients the low levels of TNF-α was associated with thrombocytosis." (PMID 34084749, 2021).
tick infestation (1 paper, 2019). Infestations with soft-bodied (Argasidae) or hard-bodied (Ixodidae) ticks. "CXCL10 and -11 play important roles in Th1-mediated immunity, and inhibition of these chemokines by several ELR− CXC-chemokine–binding evasins may mediate, in part, the suppression of Th1 responses observed in tick infestation." (PMID 31167786, 2019).
tongue tumors (1 paper, 2021). "Therefore, we further validated the expression of Th1-associated chemokine genes, including Cxcl9, Cxcl10, and Ccl5, and Th2/Treg-associated chemokine genes, including Ccl17 and Ccl22, in carcinogen-induced tongue tumors using qRT-PCR." (PMID 33921389, 2021).
toxicity (1 paper, 2022). The degree to which an agent can damage an organism. "Co-administration of DTG-based therapy and isoniazid results in significantly elevated levels of inflammatory markers such as c-reactive protein, interferon-γ, CXCL10, and other cytokines which result into liver toxicity." (PMID 35366917, 2022).
transient arthritis (1 paper, 2023). Arthritis that is not permanent. "We also found new biomarkers that correlated with reactogenicity, including transient arthritis (MCP-2, CXCL10, CXCL11, CX3CL1, MCSF, IL-15, OSM)." (PMID 38235127, 2023).
Trematode Infections (1 paper, 2021). Infections caused by infestation with worms of the class Trematoda. "Therefore, the modulation of CXCL10 serum response in S. mansoni-infected individuals with reports of ATL could also contribute to the increased susceptibility to this trematode infection." (PMID 33777015, 2021).
trigeminal neuralgia (1 paper, 2025). Trigeminal neuralgia is a nerve disorder that causes a stabbing or electric-shock-like pain in parts of the face. "In a mouse model of trigeminal neuralgia, CXCL10 binds explicitly to CXCR3, inducing activation of the PI3K/AKT signaling pathway." (PMID 41249857, 2025). "Studies have shown that CXCL10 expression is significantly increased in animal models of dorsal root nerve ligation, trigeminal neuralgia, and chronic nerve compression injury." (PMID 41249857, 2025).
ulcer (1 paper, 2022). "In a human study, urine CXCL10 levels were significantly higher in ulcer-type IC/BPS, but not in non-ulcer IC/BPS, compared with control." (PMID 35626252, 2022).
uterine cancer (1 paper, 2024). Primary or metastatic malignant neoplasm involving the uterine corpus and/or the cervix. "Multivariable analysis showed an independent association between high IDO1 and high PD-L1, high CXCL10, high STAT1, and between high IDO1 and ovarian and uterine cancers; tumors in men were significantly associated with lower IDO1 levels (all multivariable p values <0.05)." (PMID 38632994, 2024).
vaginal infection (1 paper, 2011). "Virus is able to reach the central nervous system more quickly after vaginal infection in mice deficient in CXCL10, and trafficking of NK cells and HSV-specific CD8+ T-cells (but not CD4+ T-cells) to infected tissue is impaired in both CXCL9 and CXCL10-deficient mice." (PMID 21283640, 2011).
VEXAS syndrome (1 paper, 2024). An adult-onset inflammatory disease that affects only males and is caused by somatic, not germline, mutations. "It is interesting to note that cytokine profiling in VEXAS syndrome showed increased levels of IFN-γ, CXCL-10/IP-10, and IL-8 as well as in HP." (PMID 38988571, 2024).
tumor (2,097 papers, 2002 to 2026). "Meanwhile, CXCR2- CXCL2, along with CCR5-CCL5 obviously up-regulated in tumor-adjacent tissue, and they are linked with better OS, except for CXCL10." (PMID 40087771, 2025). "CXCL9 and CXCL10, chemokines highly expressed in M1-type TAMs, especially those associated with inflammation, promote T cell recruitment, boosting anti-tumor immune responses, and are often observed in patients who respond well to immune checkpoint inhibitors." (PMID 40055311, 2025). "Old tumor cells showed reduced expression of interferon-related genes, particularly the T cell-recruiting chemokines Cxcl9 and Cxcl10, linked to their altered chromatin accessibility." (PMID 41332581, 2025). "Further analysis of RNAseq data from The Cancer Genome Atlas (TCGA) corroborated our findings, indicating a correlation between high gene expression levels, particularly CXCL10, with greater tumor mutational burden and improved survival rates." (PMID 40574841, 2025). "Oncolytic herpes simplex virus expressing CXCL10 (oHSV-CXCL10) utilises chemokine gradients to recruit peripheral NK cells while inducing tumour cells to release damage-associated molecular patterns, thereby amplifying ADCC." (PMID 41429765, 2025). "TCGA data confirmed a correlation between high gene expression and increased tumor mutational burden as well as improved survival rates, particularly for CXCL10." (PMID 40574841, 2025). "High Cxcl10 expression is associated with better survival rates in tumor patients receiving immunotherapies." (PMID 40282557, 2025). "Together, the findings revealed that Hmgb2 deficiency–induced tumor regression depended on STAT1/CXCL10/CXCR3 pathway." (PMID 40315321, 2025). "A study on tumor recurrence after liver transplantation found that the increase in circulating endothelial progenitor cells and CXCL10 was associated with a higher rate of tumor recurrence in patients who received small-volume liver transplants." (PMID 40786052, 2025). "Tumor-associated mast cells resist ferroptosis themselves, and their survival along with CXCL10 secretion promotes pancreatic ductal adenocarcinoma progression and immune evasion." (PMID 40919170, 2025). "The upregulated chemokines can attract a diverse range of innate and adaptive immune cells, for example, CCL2 attracts tumor-associated macrophages, CXCL10/11 attracts CD8+ T cells, CCL20 attracts dendritic cells, and CXCL5 attracts neutrophils." (PMID 40689422, 2025). "The methylation of these sites correlates with reduced expression of CXCL9 and CXCL10, which is associated with enhanced immune cell infiltration into the tumor microenvironment and a subsequent reduction in tumor growth." (PMID 39996888, 2025). "High CXCL10 expression within the tumor is associated with increased infiltration of cytotoxic T-cells, decreased Treg, and anti-tumor immunity." (PMID 41516196, 2025). "Recent findings show that exosome-encapsulated circPRKD3 promotes CXCL10 secretion by reprogramming tumor-associated macrophages, increasing CD8+ T cell recruitment and tumor infiltration." (PMID 40723354, 2025). "CXCL10 has a dual effect on tumor development, depending on the splice variant of the corresponding CXCR3 receptor." (PMID 40145607, 2025). "Our findings further support this concept: GLS inhibition via CB-839 not only selectively impaired MTAP-deficient tumor growth but also restored CXCL10 expression, particularly in immune co-culture." (PMID 41246302, 2025). "Higher levels of CXCL10 in NSCLC is associated with better prognosis by the recruitment of CXCR3+ CD8+ T cells to the tumour sites." (PMID 40852716, 2025). "High tumor expression of CXCL10 was associated with improved survival (mOS; 5.9 years) versus low CXCL10 expression (mOS; 3.2 years)." (PMID 41463176, 2025). "Increased levels of the Th1 chemokines C-C motif chemokine ligand 5 (CCL5), CXC-chemokine ligand 9 (CXCL9) and CXCL10 are associated with increased numbers of tumor-infiltrating CD8+ T cells." (PMID 40959109, 2025).
tumor (continued). "Within this framework, elevated serum CXCL10 is interpreted as a causal consequence of active, ongoing immune misdirection, potentially explaining why OS tumor microenvironments are frequently immune-deserted." (PMID 41516196, 2025). "An in vitro study found that a considerably higher concentration of the specific variant of CXCL10 with this structural domain is required to exhibit anti-inflammatory and anti-tumor actions." (PMID 40149853, 2025). "We investigated PD-L1 and CXCL10 levels and correlation and found that PD-L1 and CXCL10 shared the same IFNs-mediated signaling pathways in tumor cells, particularly both were associated with a better survival rate in tumor patients receiving immunotherapies." (PMID 38953994, 2024). "By encoding CXCL10, rSFV-replicon particles can enhance the recruitment of these immune cells to the tumor site, creating a more favorable environment for immune responses." (PMID 38425844, 2024). "C-X-C motif ligand 10 (CXCL10) is an estrogen-regulated, proinflammatory cytokine that has been linked to the progression of several tumor types and was associated with poor outcome in the current study." (PMID 38594742, 2024). "Previous studies have shown that the N1 markers TNFα, IL12, and CXCL10 are not only associated with neutrophils’ anti-tumor activity but also linked to ER stress signaling." (PMID 39261943, 2024). "Previous studies have demonstrated that the chemokine CXCL10 plays a key role in the recruitment of CD8 + T cells to tumor sites, and increased CXCL10 levels are associated with increased tumor infiltration of CD8 + T cells and tumor clearance or regression." (PMID 38619623, 2024). "Elevated levels of CXCL10 were associated with tumor-infiltrating CXCR3+ immune cells, including activated T cells, macrophages, DCs, monocytes, and NK cells." (PMID 39080467, 2024). "Tumor‐infiltrating cells (including NK, CD4+, and CD8+ cells), which negatively associated with the growth of tumor, were associated with increased CXCL10 levels." (PMID 39443817, 2024). "High PD-L1 and CXCL10 are associated with better survival rates in tumor patients receiving immunotherapies." (PMID 38953994, 2024). "CXCL10 influences the microenvironment of intrahepatic tumor, particularly the immune response associated with tumor in the process of carcinogenesis." (PMID 39443817, 2024). "Cytokines such as CXCL8, CXCL9, and CXCL10 are capable of attracting and activating immune cells, including macrophages and lymphocytes, causing their accumulation around the tumor." (PMID 38277205, 2024). "Proinflammatory M1‐like markers, such as CD80, TNFα, CXCL10, tend to be associated with an antitumor immune response, while macrophages expressing other proinflammatory cytokines (IL‐1β, IL‐6) can mediate tumor cell migration and cancer progression." (PMID 38037545, 2023). "Cxcl10 and Il12 are expressed in activated DCs in the tumor microenvironment and encode factors that mediate the recruitment and activation of NK cells." (PMID 37875555, 2023). "Further incorporation of CXCL13 and CXCL10 tumor transcript levels in a 3-gene index revealed that high APRIL/CXCL10/CXCL13 expression was associated with improved OS in the TCGA SKCM cohort (HR = 0.42, 95% CI 0.19-0.94; p = 0.035)." (PMID 37435077, 2023). "CD40 agonist also increased Cxcl9/Cxcl10 in KPC2a tumors and Cxcl9/Cxcl10 colocalized with both tumor-associated macrophages (TAMs) and tumor cells." (PMID 36472588, 2023). "A recent study indicated that the cholesterol synthesis was negatively associated with CXCL10 expression during tumor anti-EGFR therapy." (PMID 37828561, 2023). "The cGAS-STING pathway plays an essential part in expression of the NK-cell trafficking-associated ligand CXCL10 by irradiated tumor cells but also in the production of type-I IFN in DCs." (PMID 38264648, 2023).
tumor (continued). "Proinflammatory CD80, CXCL10, anti‐inflammatory IL‐10, and the tumor‐associated markers MMP2, MMP7, MMP12, and MGLL showed lower baseline expression and were upregulated in macrophages as well." (PMID 38037545, 2023). "One exception is the tumor driven macrophage expression of CXCL10 in osteolytic bone metastasis that was associated with increased metastases." (PMID 37404831, 2023). "The chemokine CXCL10 shapes the intrahepatic tumor microenvironment, especially impacting the tumor-associated immune-responses during hepatic carcinogenesis." (PMID 35897689, 2022). "Serum CXCL10 levels are highly associated with pathologic tumor stage, vascular invasion, and distant metastases." (PMID 35791509, 2022). "Nevertheless, the combination of CXC chemokines with known tumor markers (e.g., CXCL10 and CA19-9) increased the diagnostic potential compared to either parameter alone, showing an AUC value of 0.903." (PMID 36077611, 2022). "Bulk RNA sequencing of DRGs from tumor-bearing mice detected activation of gene expression pathways associated with elevated cytokine and chemokine signaling, including CXCL10." (PMID 35962398, 2022). "For example, CXCL10 can make a variety of antitumor lymphocytes chemotactic to tumor tissues, such as CD8+ T cells, and is associated with T-lymphocytes infiltration in solid tumors." (PMID 36238297, 2022). "Chemokines such as C-X-C Motif Chemokine Ligand 9 (CXCL9) and CXCL10 stimulate T cell trafficking and infiltration into the tumor, where T-cell-mediated cytotoxicity liberates more tumor-associated antigens to further propagate the cancer-immunity cycle." (PMID 36700235, 2022). "In the present study, the function of the chemokine CXCL10 during fibrosis-associated hepatocarcinogenesis was analyzed with specific focus on its impact in shaping the tumor microenvironment." (PMID 35897689, 2022). "While we did observe only a slight, non-significant increase in Cxcl9 ascites concentration upon Brca2 loss, Cxcl10 was more than fivefold higher than in Brca2WT tumours." (PMID 35314795, 2022). "Since tumor-associated angiogenesis is a hallmark of cancer progression, we analyzed the tumor vascularization of tumorigenic WT and Cxcl10−/− mice." (PMID 35897689, 2022). "It is believed that in various human cancers, low expression of CXCL10 at the tumor site is significantly associated with poor prognosis." (PMID 36479091, 2022). "Cxcl10 deficiency attenuated hepatocarcinogenesis by decreasing tumor cell proliferation as well as tumor vascularization and modulated tumor-associated extracellular matrix composition." (PMID 35897689, 2022). "The outcomes show a significant increase in tumor purity and Tregs activity in the high-risk group, and notably, a significant increase in memory immune cells and CXCL10 in the high-risk group." (PMID 36060936, 2022). "The activation of hypoxia signaling increases the expression of adipokines, especially the pro-inflammation adipokines (including CCL2, CXCL8, CXCL10, IL-18, IL-1α and Oncostatin M), which is involved in the recruitment of tumor-associated immune cells." (PMID 35350384, 2022). "DCR following treatment was 71%, in association with improved IFNγ production, CXCL9/CXCL10 chemokine expression and increased intra-tumor T cell infiltration, all representative of an immune-stimulatory environment." (PMID 36428727, 2022). "In vitro migration studies underlined that low concentrations of CXCL9 and CXCL10 produced by tumor endothelial cells promoted chemotaxis." (PMID 35626062, 2022). "Both UMAP plot and violin plot demonstrated that tumor associated macrophages were more likely the main source of CXCL10 and its receptor CXCR3 was highly expressed in T cells." (PMID 34276760, 2021). "Recently, expression of the proinflammatory cytokines CXCL9 and CXCL10 by tumor-associated macrophages has been shown to be essential for tumor response to anti-PD-L1 therapy." (PMID 34663877, 2021).